MTOR (mechanistic target of rapamycin kinase)
Diseases named in the same sentence as MTOR in open-access papers (continued):
Sharing a sentence is not in itself a finding about the gene and the disease.
breast cancer (continued). "Preclinical evidence demonstrated that ketogenic diet was able to reduce spikes in serum insulin and glucose and suppress downstream PI3K/mTOR signaling in PI3Ki-treated mice better than metformin, and also improve response to PI3Ki in multiple tumor types including breast cancer." (PMID 35016012, 2022). "IHC staining revealed that tumors in the ZDHHC22 group had a lower percentage of Ki-67 positive cells and mTOR expression than tumors in the other two groups, indicating ectopic ZDHHC22 expression suppressed the proliferation and expression of mTOR protein of breast cancer." (PMID 35541896, 2022). "The PI3K/mTOR axis is frequently activated in breast cancer 9,10,12." (PMID 35673573, 2022). "Subsequently, the AKT/mTOR axis was detected both in breast cancer and gastric cancer." (PMID 36060798, 2022). "Incubation of gastric or breast cancer cells with ADO increases EMT gene expression, associated with A2AR/A2BR activation and the Akt-mammalian target of rapamycin (mTOR) or adenylyl cyclase (AC)/protein kinase A (PKA)/cyclic adenosine monophosphate (cAMP) pathway." (PMID 36072596, 2022). "In contrast, GABARAP suppressed breast cancer progression through the AKT/mTOR signaling pathway; however, how GABARAP suppressed the signaling pathway remains unclear." (PMID 36430876, 2022). "Indeed, the PI3K/Akt/mTOR axis can be used in the long term by breast cancer cells to escape their reliance on ER signaling and consequently enhance resistance to tamoxifen." (PMID 36428613, 2022). "Based on these studies, tamoxifen resistance in breast cancer may be related to AKT/mTOR/AMPK signaling." (PMID 36059650, 2022). "In addition, clinical trials are also necessary to further validate mTOR as a potential therapeutic target for flavonoids in chemoresistant breast cancer." (PMID 35795855, 2022). "The expression of these enzymes is regulated by SREBP1 and mTOR signaling in breast cancer." (PMID 36551752, 2022). "Based on the results, it was hypothesized that YTHDF2 may promote LUSC cell proliferation by activating the AKT/mTOR signaling pathway which is known to play a pivotal role in multiple types of cancer, such as breast cancer and ovarian carcinoma." (PMID 34996459, 2022). "The mTOR inhibitor (AZD8055) could inhibit the tamoxifen resistance in breast cancer cells by suppressing the expression of HSPB8." (PMID 35069935, 2022). "A previous study also showed that SLC7A5 regulated AKT/mTOR activation in breast cancer." (PMID 35986300, 2022). "This study also considered how dual inhibition of polyamine and mTOR pathways might enhance the inhibition of breast cancer cells growth." (PMID 36135836, 2022). "mTOR inhibitors have been approved for use in postmenopausal women with HR-positive breast cancer." (PMID 35795855, 2022). "Authors focused on ibrutinib (Selleck Chemicals, Houston, TX, USA) and ibrutinib combined with dactolisib (Selleck Chemicals, Houston, TX, USA), a phosphoinositide 3-kinase/mammalian target of rapamycin kinase (PI3K/mTOR) inhibitor, on ten different breast cancer cell lines in vitro." (PMID 35456016, 2022). "Furthermore, accumulating evidence indicates that canagliflozin can regulate WNT/β-catenin or AMP-activated protein kinase/mammalian target of rapamycin (AMPK/mTOR) signaling, so that to block the growth of hepatocellular carcinoma and breast cancer." (PMID 36457493, 2022). "Therefore, small-molecule inhibitors targeting the key players, PI3K, AKT, and mTOR can reverse the drug resistance and self-renewal abilities of breast cancer stem-like cells." (PMID 35392236, 2022). "PI3K/Akt/mTOR signaling pathway was necessary for tumor cells’ survival (e.g., breast cancer, head and neck cancer (Marquard and Jücker, 2020), and lung cancer)." (PMID 35047507, 2021).
breast cancer (continued). "It was also found that resistant colonies emerged after the exposure of the MCF-7 breast cancer cell line to high concentrations of a first generation mTORC1 inhibitor, rapamycin, or a second generation mTOR ATP competitive inhibitor (AZD8055) for three months." (PMID 33572326, 2021). "The mTOR inhibitor, everolimus, reduced mammary tumor size in obese mice." (PMID 34201429, 2021). "It was demonstrated that SPS could promote apoptosis in MCF-7 breast cancer cells by regulating the expression of Bcl-2 and Bax, and also induce apoptosis by blocking the PI3K/Akt/mTOR pathway in MDA-MB-435 human breast cancer cells." (PMID 34744747, 2021). "Clinical trials are needed to confirm that PTEN‐altered breast cancer harbors ICPI resistance that may be reversed by PI3K/AKT/mTOR inhibitor mono‐ or combination therapy." (PMID 33314633, 2021). "To test the efficacy of a combination of HER2 blockade with mTOR inhibition as a potential therapeutic strategy to overcome resistance to trastuzumab in HER2-positive breast cancer cell line (BCCL) models, we first developed four different cellular models with acquired resistance to trastuzumab." (PMID 34204960, 2021). "However, it is also true that the CCL5-CCR5 interaction has also been reported to promote breast cancer proliferation by regulating metabolic events and mTOR activation." (PMID 33671956, 2021). "Based on preclinical studies suggesting that up-regulation of the PI3K-AKT-mTOR signaling pathway causes acquired resistance to CDK4/6 inhibitors, the mTOR inhibitor everolimus and PI3K inhibitor alpelisib have been clinically used to manage CDK4/6 inhibitor-resistant breast cancer." (PMID 32860163, 2021). "Whether mTOR is a major regulator of COL17-mediated breast cancer cell growth needs to be clarified using mTOR inhibitor-treated cell." (PMID 34293053, 2021). "We acknowledge that the body fatness measurement in this study may not accurately reflect the specific adiposity compartments that are most relevant to mTOR pathway activation and breast cancer etiology." (PMID 34330319, 2021). "Phosphatidylinositol 3-kinase/protein kinase B/mammalian target of rapamycin (PI3K/AKT/mTOR) pathway is one of the several self-renewal pathways existing in breast cancer cells and inhibitors of this pathway may reduce ‘stemness’ of cancer cells." (PMID 34208799, 2021). "In addition, PI3K inhibitors and BEZ235 (dual PI3K/mTOR inhibitor) suppress trastuzumab-resistant breast cancer cell proliferation by inhibiting the PI3K/AKT/mTOR pathway." (PMID 33790792, 2021). "Our hypothesis is also supported by a recent study, reporting that PKCε signaling can negatively impact on autophagy directly converging on MTOR in breast cancer cells." (PMID 34638477, 2021). "Similarly, the other article reported that Dhw-208 inhibits the growth of human breast cancer cells by inhibiting the PI3K/AKT/MTOR signaling pathway." (PMID 33676540, 2021). "The PI3K/Akt/mTOR pathway has been well known to interact with the estrogen receptor (ER)-pathway and to be also frequently upregulated in aromatase inhibitor (AI)-resistant breast cancer patients." (PMID 34503187, 2021). "The level of autophagy in MCF7 breast cancer (BC) cells can be increased by mTOR inhibitor, rapamycin (RAPA), delayed the attendance of Rad51 and BRCA1 protein localization, and prolonged the expression of damage characteristic sensor γ-H2AX, resulted in the accumulation of DSB damage." (PMID 34321364, 2021). "Currently, in addition to the MTOR pathway inhibitor everolimus which is approved for treating breast cancer patients with ER+ disease, additional novel MTOR inhibitors are in early and late-stage clinical trials for the treatment of a wide variety of solid tumors." (PMID 34282751, 2021). "Abnormal activation of PI3K/Akt/mTOR has been found in about 70% of breast cancer cases." (PMID 33986665, 2021). "Mammary tumors in obese female mice showed higher mTOR signaling than mammary tumors in lean mice." (PMID 34201429, 2021).
breast cancer (continued). "We observed an inverse association between BMI ≥ 35 vs. < 25 and p-mTOR-negative/low breast cancer overall and among women with ER– tumors." (PMID 34330319, 2021). "Summary clinical RCT trials of PI3K/AKT/mTOR inhibitors in breast cancer." (PMID 33790792, 2021). "The recent TRINITI-1 trial (NCT02732119) differs from the others that have explored the use of mTOR inhibitors in ER+ breast cancer patients because patients in this trial were actually treated with ribociclib as part of their regimen even though they had previously progressed on a CDK4/6 inhibitor." (PMID 34830174, 2021). "Additionally, EHop-016 sensitizes HER2 overexpressing trastuzumab sensitive and resistant breast cancer cells to trastuzumab, and was recently shown to overcome therapy resistance by combined cancer therapy with Akt/mTOR inhibitors." (PMID 34074257, 2021). "EMP3 blocks Akt/mTOR pathway in breast cancer cells, suggesting that this pathway may mediate EMP3-induced suppression of DNA replication, cell growth, and DNA damage repair." (PMID 34511602, 2021). "The PI3K/AKT/mTOR signaling inhibits ferroptosis by SREBP-regulated lipogenesis in breast cancer." (PMID 34122108, 2021). "Overall, PI3K/AKT/mTOR pathway inhibitors show the potential ability to restore sensitivity to standard treatments, which is an attractive strategy in overcoming resistance during breast cancer treatment." (PMID 33790792, 2021). "The mechanistic target of rapamycin (mTOR) is a known therapeutic target in breast cancer." (PMID 33124043, 2021). "In two independent human breast cancer cohorts, encompassing nearly 3,000 tumor samples, transcriptional footprint-based analysis uncovered a positive linear association between transcriptionally-inferred PI3K/AKT/mTOR signaling scores and stemness scores." (PMID 34762647, 2021). "Currently, there are several ongoing clinical trials evaluating triple combination therapy consisting of endocrine therapy, CDK4/6i, and other inhibitors of the PI3K/AKT/mTOR pathway in ER+ advanced breast cancer following progression on a CDK4/6i regimen (NCT02871791, NCT02732119)." (PMID 34433817, 2021). "As a logical consequence, among the many causes that have been associated with resistance to anti-HER2 therapies in breast cancer, dysregulations in the signalling of the PI3K/AKT/mTOR pathway seem to play an important role, as we confirmed in our cellular models of acquired resistance." (PMID 34204960, 2021). "The PI3K/AKT/mTOR pathway is an important therapeutic target for treatment of breast cancer." (PMID 33669867, 2021). "mTOR is an important regulator of autophagy, including in breast cancer." (PMID 34202777, 2021). "Clinical trials targeting mTOR in HER2-positive breast cancer." (PMID 34208071, 2021). "Moreover, it is reported that H2S regulates the growth of human breast cancer cells or thyroid carcinoma cells through PI3K/Akt/mTOR and RAS/RAF/MEK/ERK signaling pathways." (PMID 33903672, 2021). "In particular, heterotypic adherens junctions between breast cancer cell-derived CDH1 and CDH2 in an osteogenic niche can support bone colonization of circulating breast cancer cells and stimulate the mechanistic target of rapamycin (mTOR) pathway-driven micrometastasis formation." (PMID 34831167, 2021). "Our results might impact the choice of the best therapeutic approach for advanced, endocrine-resistant ER+ breast cancer with an upregulated PI3K/PTEN/Akt/mTOR pathway." (PMID 33809171, 2021). "The PI3K/AKT/mTOR pathway is crucial in breast cancer, as it is involved in tumor proliferation, survival, motility, metabolism and anti-tumor therapy resistance, as well as the immune response, and the activated PI3K/Akt signaling pathway is involved in poor prognosis." (PMID 34834420, 2021).
breast cancer (continued). "Furthermore, vitamin D has been reported to affect the mTOR pathway: in vitro treatment with vitamin D and vitamin D analogs decreased mTOR activity in osteoblast and human breast cancer cell line." (PMID 33670988, 2021). "The tumorigenic function of the SREBF1 transcription factor, which was found to be overexpressed and positively associated with metastasis and poor prognosis in breast cancer patients, has been linked to oncogenic activation of the PI3K/AKT/mTOR signaling pathway." (PMID 34439480, 2021). "In addition to being HER2 positive, 21MT-1 cells had hyper-activated p-Ser473 Akt, a kinase involved in the PI3K/Akt/mTOR pathway frequently activated in breast cancer." (PMID 34842634, 2021). "Additionally, miR-221 has been illustrated to promote breast cancer resistance to adriamycin via modulation of the PTEN/Akt/mTOR signaling pathway in 25 breast cancer samples." (PMID 34639152, 2021). "As a result of these studies, several therapies that combine anti-estrogens that degrade ERα with PI3K/AKT/mTOR inhibitors targeting growth factor signaling or CDK4/6 inhibitors targeting cell cycle machinery are used clinically to treat recurrent ERα+ breast cancers." (PMID 33498407, 2021). "In order to extend the knowledge, we assessed the prevalence of the E542K, E545K, H1047R mutations within the PIK3CA gene and the E17K mutation within the AKT1 gene, and the expression of the PIK3CA, PIK3R1, PTEN, AKT1, mTOR genes in a cohort of patients with breast cancer." (PMID 33669698, 2021). "Thus, UASR1 plays an oncogenic role in breast cancer cells through activation of the AKT/mTOR signaling pathway." (PMID 33672592, 2021). "Interestingly, a recent study showed that inhibition of SLC1A5/ASCT2 significantly reduced glutamine uptake in a human breast cancer cell line in a subtype‐dependent manner, with suppression of mTOR signaling, cell growth, and cell cycle progression." (PMID 34003553, 2021). "Furthermore, when we examined the expression of cellular signal molecules, D4476 reproduced many of the effects of CSNK1G2 on the PI3K/AKT/mTOR signaling system in breast cancer cells." (PMID 33861751, 2021). "HIF-2α modulates CD44 to enhance activation of CSCs by PI3K/AKT/mTOR signaling in breast cancer." (PMID 35004266, 2021). "As mTOR is a downstream effector in the PI3K and AKT signaling pathways, we determined whether mTOR activity was altered by modulation of CSNK1G2 in breast cancer cells." (PMID 33861751, 2021). "Our findings suggest that in this population composed of predominately Black women, body fatness is associated with breast cancer differently for p-mTOR overexpression and p-mTOR negative/low expression." (PMID 34330319, 2021). "Although inhibitors targeting the HER2 receptor have been successful in treating HER2-positive breast cancer, anti-HER2 therapy is associated with a high risk of recurrence and drug resistance due to stimulation of the PI3K-Akt-mTOR signaling pathway and glycolysis." (PMID 34208071, 2021). "The BEZ-235 can inhibit PI3K/AKT/mTOR pathway, which is dysregulated in breast cancer." (PMID 33577560, 2021). "What is more, emodin restrained EMT through the ILK/AKT/mTOR signalling pathway in breast cancer." (PMID 33531984, 2021). "Among these, the PI3K/AKT, AMPK, and mTOR pathways are activated in breast cancer." (PMID 34552932, 2021). "Because inhibition of the PI3K/AKT/mTOR axis results in enhanced HER2 signalling in HER2-overexpressing breast cancer, especially increased expression of HER2 and HER3, targeting both pathways could prevent the development of resistance." (PMID 34204960, 2021).
breast cancer (continued). "In the sensitivity analysis restricted to invasive breast cancer cases vs. controls, the overall associations of body size variables with p-mTOR overexpressed and p-mTOR negative/low breast cancer remained the same as those in all cases vs. controls." (PMID 34330319, 2021). "Because inhibition of the PI3K/AKT/mTOR axis results in enhanced HER2 signalling in HER2-overexpressing breast cancer, especially in increased expression of HER2 and HER3, targeting both pathways could prevent the development of resistance." (PMID 34204960, 2021). "Clinically, mTOR inhibitor everolimus is known to increase progression-free survival when given in combination with exemestane compared to exemestane alone in post-menopausal women with advanced hormone receptor-positive breast cancer; thus, mTOR is a proven target in breast cancer." (PMID 33663585, 2021). "The loss of two important factors of the PI3K/AKT pathway, phosphatase and tensin homolog (PTEN) and mammalian target of rapamycin (mTOR), drives the induction of PD-L1 protein levels in breast cancer cells, as well as tumor samples from breast cancer patients." (PMID 33506060, 2021). "Additionally, the mTOR pathway in HER2-positive breast cancer mediates a metabolic shift from glycolysis to OXPHOS to further facilitate the nutrients required for tumor growth." (PMID 34208071, 2021). "Bioinformatics analysis and Western blot analysis helped us find that GARS may influence the malignant progression of breast cancer through the AKT/mTOR pathway." (PMID 34953500, 2021). "The PI3K/Akt/mTOR axis is responsible for growth and progression of CSCs in breast cancer." (PMID 34769099, 2021). "Finally, our data suggested that the lncRNA signature can serve as a promising indictor for measuring response to mTOR inhibitors in breast cancer patients." (PMID 34581026, 2021). "However, no clinical studies have assessed the immunoregulatory effects of mTOR inhibitors in breast cancer patients so far." (PMID 34315439, 2021). "It is also known that leptin-induced mammalian target of rapamycin (mTOR) activation may have implications for obesity-related pathophysiological conditions such as breast cancer." (PMID 34684340, 2021). "mTOR hyperactivity, autophagy and other metabolic processes, including mitochondrial functions, could be targeted in breast cancer progression." (PMID 34360785, 2021). "However, the highest cytotoxic effect was obtained for the FMCp cell line (43.3% of cytotoxicity), corroborating the data that mTOR is frequently overexpressed in HER2-negative breast cancer." (PMID 33800900, 2021). "Moreover, everolimus induced apoptosis by decreasing Bcl-2, phosphoinositide 3-kinase (PI3K), protein kinase B (AKT), and mTOR expression levels in breast cancer cells." (PMID 34361836, 2021). "Moreover, inhibition of PI3K/Akt/mTOR pathway has also been observed in ER-negative breast cancer cells (Bcap37) treated with CT at low concentration and ERα-positive breast cancer cells." (PMID 33544704, 2021). "Similarly, BELLE-3 was designed to include Luminal A (HR+/HER-) breast cancer patients that had been previously unsuccessfully treated by prior endocrine therapy and mTOR inhibitors." (PMID 34298731, 2021). "For instance, flavonoids and isoflavones extracted from Tephroseris kirilowii and Astragalus membranaceus, well-known herbs used in Chinese traditional medicine, resulted in induced apoptosis by inhibiting the PI3K/AKT/mTOR pathway in various types of human breast cancer cells." (PMID 34044827, 2021). "In addition, delphinidin induces apoptosis and autophagy by downregulating the expression of caspase-3, caspase-9, and AKT/mammalian target of rapamycin (mTOR) pathway in breast cancer cells." (PMID 34512232, 2021). "Also, genes in PI3K/Akt/mTOR signaling pathways were upregulated in ER+/PR- breast cancer patients compared with ER+/PR + patients." (PMID 34022815, 2021).